AR (androgen receptor)
Diseases named in the same sentence as AR in open-access papers (continued):
Sharing a sentence is not in itself a finding about the gene and the disease.
prostate carcinoma (continued). "The DPYSL5 protein staining intensity significantly correlated with SYP, CGA and NCAM in prostate cancer patients and showed an inverse correlation with AR and PSA." (PMID 38238517, 2024). "Other pathways, such as prostate cancer, are involved in the pathogenesis of prostate cancer, mainly related to the androgen receptor (AR) signaling pathway." (PMID 39470548, 2024). "Based on the frequent high-level AR expression in prostatic adenocarcinoma, AR IHC is applied for the distinction of poorly differentiated prostatic cancer from urothelial carcinoma." (PMID 38790919, 2024). "c-Myc overexpression contributes to suppression of AR activity, with low AR activity and high c-Myc being typical signatures of aggressive prostate cancer." (PMID 39253786, 2024). "This remodeled AR signaling (ARS) and NE genes in the vicinity of chromatin, which in turn regulated the expression of ARS and NE genes and activated the AR signaling pathway, ultimately promoting the transformation of prostate cancer to NEPC." (PMID 39655078, 2024). "Androgen receptor signalling remains an important prostate cancer driver, even in the advanced disease stage." (PMID 39267821, 2024). "A greater expression of this long noncoding RNA (lncRNA) in prostate cancer contributes to the development of resilience in the face of AR inhibitors or androgen deprivation." (PMID 39512820, 2024). "To confirm this finding, we utilized a distinct AR-positive prostate cancer cell line, 22Rv1, which is commonly used to model CRPC." (PMID 39117800, 2024). "In vitro, A4B17 downregulates AR target gene expression, and inhibits proliferation of AR-positive prostate cancer cells." (PMID 39359255, 2024). "Targeting AR to alter transcriptional signaling and block disease progression is a common therapeutic strategy in prostate cancer." (PMID 38566104, 2024). "Human prostate cancer arises from a luminal androgen receptor-positive cell and is sensitive to testosterone levels." (PMID 38564578, 2024). "The significance of AR in prostate cancer biology has been well documented and, as a result, multiple therapies target this important pathway." (PMID 39858418, 2024). "Inhibition of androgen receptor (AR) signaling is the main treatment strategy in advanced prostate cancer (PCa)." (PMID 39300962, 2024). "KLK3 is commonly used as a marker for AR activity and for monitoring the progression of prostate cancer." (PMID 39598420, 2024). "Further analysis using prostate cancer gold peak datasets (detailed in the Experimental Section) found that RECWAS identified 3 novel AR and 6 H3K27ac gold peaks, in contrast to CWAS which identified only one H3K27ac gold peak within these datasets." (PMID 39099406, 2024). "To investigate the effect of AR inhibition on race-specific gene expression changes, we generated in-silico patient-specific prostate cancer Boolean networks." (PMID 38566104, 2024). "IHC findings revealed that DDIT4 expression was decreased in prostate cancer, whereas AR expression was up-regulated." (PMID 38384328, 2024). "Prostate cancer (PC) is driven by aberrant signaling of the androgen receptor (AR) or its ligands, and androgen deprivation therapies (ADTs) are a cornerstone of treatment." (PMID 39207857, 2024). "This action prevents translocation, DNA binding androgen receptor-mediated transcription, resulting in the effective inhibition of prostate cancer cell proliferation." (PMID 38699643, 2024). "For instance, EZH2 has been observed to positively regulate androgen receptor gene expression in castration-resistant prostate cancer." (PMID 39120328, 2024). "Combined AR intervention and irradiation resulted in decreased clonogenic survival of prostate cancer cells or tumor progression in mice models." (PMID 38956684, 2024).
prostate carcinoma (continued). "Many studies have discussed the interactions between AR signaling and other molecular pathways in prostate cancer progression, highlighting the potential for combination therapies to enhance treatment efficacy and overcome resistance mechanisms." (PMID 39184676, 2024). "Subsequently, it was discovered that GR acts as a tumor suppressor in AR-positive prostate cancer, with glucocorticoids inhibiting tumor cell growth by restraining the activity of MAPK signaling." (PMID 39027480, 2024). "In conclusion, these data demonstrate that concurrent blockade of the PI3K/AKT/mTOR and AR pathways has superior antitumor efficacy and induces apoptosis in androgen-sensitive prostate cancer cell lines and PDX models." (PMID 38225213, 2024). "The androgen receptor (AR) is a key driver of prostate cancer (PCa) and, as such, current mainstay treatments target this molecule." (PMID 39001502, 2024). "In the relentless pursuit of improved prostate cancer management, understanding and targeting AR-Vs, given the availability of a non-invasive blood-based AR-V7 test, is a necessary step toward addressing therapeutic resistance and improving patient outcomes." (PMID 38201308, 2024). "Androgens are known to be essential for both normal prostate tissue and prostate cancer tissue, exerting a strong influence on the lipid composition in meibomian gland secretions through the androgen receptor." (PMID 39274527, 2024). "The standard treatment for metastatic prostate cancer is androgen-deprivation therapy (ADT) with an antiandrogen since the progression of prostate cancer usually depends on androgen receptor signaling." (PMID 38339260, 2024). "Androgen receptor (AR) drives prostate cancer (PC) growth and progression, and targeting AR signaling is the mainstay of pharmacological therapies for PC." (PMID 38416822, 2024). "Other AhR antagonists have similarly demonstrated their ability to block AR activity and reduce tumor growth, providing a robust strategy for targeting hormone-refractory prostate cancer." (PMID 39184676, 2024). "The results suggest that MDM2 is an E3 ligase inducing AR polyubiquitination and protein degradation in prostate cancer cells." (PMID 38410785, 2024). "This study also developed LLPS inhibitors targeting the AR, which were able to inhibit the transcriptional activity of the AR and effectively inhibit the tumor growth of prostate cancer cells expressing drug-resistant mutant AR in vivo." (PMID 39253293, 2024). "In primary human prostate cancer samples, a link between AR signature and DNA repair genes was demonstrated." (PMID 38956684, 2024). "Since AR is involved in prostate cancer cell migration, we were interested to determine if MDM2 inhibition would affect these processes." (PMID 38410785, 2024). "Recently, VNPP433-3β was found to inhibit cancer stem cells (CSCs) in prostate cancer, possibly by degrading AR." (PMID 39598525, 2024). "Androgen receptor targeting agents (ARTAs) are designed to block androgen receptors, which are critical for the growth of prostate cancer cells." (PMID 39830537, 2024). "Many studies on antioxidants and prostate cancer have focused on suppressing ROS to, in turn, suppress AR expression and signaling." (PMID 39000269, 2024). "SRC-1 can functionally promote the transactivation of AR and participate in the ligand-independent activation of AR by IL-6 in prostate cancer cells." (PMID 38553750, 2024). "Prostate cancer is one of the most common cancers among males globally, with AR playing a pivotal role in its pathogenesis." (PMID 39500878, 2024). "Prostate cancers that escape therapy targeting the androgen receptor signaling pathways via phenotypic plasticity are currently untreatable." (PMID 39113611, 2024). "This reveals binding sites for several known prostate cancer regulatory TFs, including AR, ERG, ETS1 and FOXA1 in a putative enhancer region that does not belong to the set of GWAS SNPs." (PMID 37971305, 2024).
prostate carcinoma (continued). "Flutamide, a selective AR antagonist, has been used clinically to treat patients with prostate cancer." (PMID 38900572, 2024). "The normal development and maintenance of the prostate depend on androgens acting through the androgen receptor, which is also essential for the development and progression of prostate cancer." (PMID 39274527, 2024). "One study used HiC to demonstrate that the chromatin structure of the androgen receptor (AR) locus is altered in prostate cancer." (PMID 39544254, 2024). "The normal growth and function of the prostate are heavily dependent on the androgen and androgen receptor (AR) pathway, which is also crucial in the development and progression of prostate cancer." (PMID 39296545, 2024). "For nearly a century, fundamental observations that prostate cancer (PCa) cells nearly always require AR stimulation for sustained proliferation have led to a unidirectional quest to abrogate such a pathway." (PMID 39796704, 2024). "We have previously developed very potent HDAC inhibitors conjugated with AR antagonists, which were shown to be highly cytotoxic for prostate cancer cells in vitro and in vivo." (PMID 38254786, 2024). "These natural compounds target specific pathways like the androgen receptor signaling and prostate cancer stem cells, offering promising therapeutic potentials for prostate cancer management." (PMID 39062777, 2024). "In prostate cancer, AHR has been implicated in regulating AR signaling, a key driver of tumor growth and progression." (PMID 39600743, 2024). "Following the widespread clinical use of next-generation ARPIs, the proportion of AR-null prostate cancer, including neuroendocrine prostate cancer (NEPC) and double-negative prostate cancer (DNPC), has subsequently risen as a means of drug resistance." (PMID 38254880, 2024). "Prostate cancer (PC) cell growth typically relies on activation of androgen receptor (AR) signaling by systemic/circulating androgens." (PMID 39092562, 2024). "Upon ADT, some prostate cancers develop further genetic alterations (e.g., amplification of the AR locus) that make them “castration-resistant” (i.e., refractory to ADT)." (PMID 36674949, 2023). "ANXA7 is known to interact with the androgen receptor (AR), a key regulator of prostate cancer growth." (PMID 37240163, 2023). "HDACs are also overexpressed in prostate cancers and required for functional androgen receptor signaling." (PMID 37104249, 2023). "Lutetium 177Lu vipivotide tetraxetan is used to treat prostate cancer after the administration of other therapies (such as androgen receptor (AR) pathway inhibition and taxane-based chemotherapy)." (PMID 36986436, 2023). "LncRNAs can contribute to the pathogenesis of prostate cancer via modulation of androgen receptor (AR) signaling, ubiquitin–proteasome degradation process of AR or other important signaling pathways." (PMID 37025585, 2023). "In most cases, prostate cancer is an androgen-dependent condition, and the androgen receptor (AR) signaling pathway is critical to its initiation and development." (PMID 37629142, 2023). "ABI1 was recently shown to regulate the transcriptional activity of AR in prostate cancer cells and can prove to be a novel and effective drug target for AR+ TNBC cells." (PMID 38067367, 2023). "Prostate cancer is driven by AR signaling, and several compounds targeting AR pathway and androgen synthesis have been used for advanced prostate cancer treatment." (PMID 36614243, 2023). "Aberrant AR signaling is fundamental to prostate cancer growth, metastasis, metabolic reprogramming and ultimately to its lethality." (PMID 36674820, 2023). "We selected the androgen-dependent growth of a prostate cancer cell line as a screening indicator because androgen-dependent growth reflects the androgen activity and can detect multiple AR signaling steps." (PMID 37744273, 2023).
prostate carcinoma (continued). "Recently, the effect of a canonical AR antagonist (bicalutamide: Bic) in chromatin remodeling and expression profile in a human prostate cancer cell line (LNCaP cells) was examined." (PMID 37025180, 2023). "Prostate cancer is driven by androgen receptor (AR) activation, where testosterone (T) and 5α-dihydrotestosterone (DHT) are the most potent AR ligands and are responsible for the majority of downstream AR signaling." (PMID 37772993, 2023). "In summary, our study demonstrates that androgen receptor degradation occurs through the novel activation of BiP and suggests a new therapeutic approach for prostate cancer." (PMID 37046780, 2023). "The initiation and progression of prostate cancer (PCa) in humans is initially reliant on androgen receptor (AR) signaling." (PMID 37189720, 2023). "Small molecules targeting the dimer interface pocket locatedat the ligand-binding domain of androgen receptor (AR) are capableof suppressing AR signaling and combating prostate cancer." (PMID 37122451, 2023). "In prostate cancer, androgen receptor (AR) signaling mediates SCAP upregulation and promotes SREBP activity." (PMID 37653037, 2023). "Here, we demonstrate that androgen-induced, AR-mediated LD metabolism and the autophagy that promote prostate cancer cell proliferation requires Sigma1 and is downstream of AR signaling." (PMID 37874216, 2023). "For example, XIST has been characterized as a tumor suppressor in prostate cancer, but it functions as a ceRNA in bladder cancer and increases AR signaling, an important pathway in tumor development and drug resistance." (PMID 36902032, 2023). "Here, we show that androgens activate YAP/TAZ via the androgen receptor (AR) in prostate cancer (PCa), and that this activation is differential." (PMID 37385752, 2023). "Androgen deprivation therapy (ADT) and AR inhibition are the main strategies for prostate cancer treatment." (PMID 36776288, 2023). "Based on its natural role, AR’s involvement in prostate cancer has been prominent and known for many years." (PMID 38203506, 2023). "There is evidence that the AR also regulates the EMT in prostate cancer and ADT has been shown to activate EMT and neuroendocrine differentiation (NED), which will be discussed later in this review." (PMID 37830741, 2023). "AR dysregulation serves as a signal for hormonal disorders such as androgen insensitivity and prostate cancer." (PMID 38067367, 2023). "It has been recognized that UGT2B15 is only expressed in the AR-positive cell lines and UGT2B15 expression is markedly repressed by AR to sustain pro-proliferative functions of androgen in prostate cancer." (PMID 38136265, 2023). "This crosstalk was already established for GR and estrogen receptor α (ERα) in breast cancer and for GR and androgen receptor (AR) in prostate cancer and influences therapy responsiveness." (PMID 37578563, 2023). "Consistent with previous studies, DKO mice spontaneously developed adenocarcinoma prostate cancer characterized by androgen receptor-positive features, whereas TKO mice developed androgen receptor-negative neuroendocrine prostate cancer." (PMID 38016952, 2023). "MED19, a component of the mediator complex and a co-regulator of the androgen receptor (AR), is pivotal in prostate cancer cell proliferation." (PMID 37880276, 2023). "It has been reported that AR overexpression increases the transcription of genes involved in the cell cycle, resulting in increased proliferation of prostate cancer cells." (PMID 37900178, 2023). "The protein methyltransferase KMT5A has been shown to interact with the androgen receptor and was proposed to offer therapeutic benefits to prostate cancer patients." (PMID 37509260, 2023). "In prostate cancer cells, AR is a well-defined PARP7 substrate for which the ADP-ribosylation sites have been defined and characterized by mutagenesis." (PMID 37077937, 2023).
prostate carcinoma (continued). "The androgen receptor (AR), whose main functions are promoting the growth, differentiation, and survival of epithelial cells in the prostate, plays a fundamental role in prostate cancer." (PMID 36677878, 2023). "Accumulating evidence indicates that androgen signaling and AR expression play important roles in prostate cancer, even after the transition into the CRPC state." (PMID 37025180, 2023). "This dataset comprises bulk RNA-seq data from an extensively annotated study on the progression of prostate cancer, focusing on the responsiveness and development of resistance to AR-targeted therapies." (PMID 38105227, 2023). "Enzalutamide exerts its therapeutic effect by inhibiting the androgen receptor (AR) signaling pathway, which plays a crucial role in the development and progression of prostate cancer." (PMID 37670963, 2023). "Aberrant expression of AR contributes to the progression of prostate cancer, making this protein a recognized therapeutic target in this context." (PMID 36880517, 2023). "The full-length androgen receptor (AR-FL) is a driver of prostate cancer (PC) by acting as a transcription factor, thereby facilitating disease progression." (PMID 37016463, 2023). "At diagnosis, nearly all prostate cancers are adenocarcinomas driven by androgen receptor (AR) signaling." (PMID 37440313, 2023). "The Au-AR pep-PROTAC was found to stimulate the degradation of AR and AR-V7 and reduce the growth of AR- and AR-V7-positive prostate cancer cell lines, including LNCaP, C4-2, and CWR22Rv1, with IC50 values of 230.8 nM, 248.1 nM, and 126.9 nM, respectively." (PMID 37175108, 2023). "Employing ER or AR antagonists in tandem with ferroptosis induction effectively impedes the growth of ER + breast cancer and AR + prostate cancer, even in cases of resistance to individual hormonal therapies." (PMID 37840106, 2023). "Down-regulation of the androgen receptor protein was the key to therapeutic approaches of AR-dependent prostate cancer." (PMID 37191432, 2023). "LNCaP95 cells are a model of castration-resistant prostate cancer that demonstrate sustained AR expression, cellular plasticity and acquire enzalutamide resistance through activation of the transcription factor Snail." (PMID 37228586, 2023). "The pathogenetic role of the AR pathway is evident in the majority of prostate cancer cases, both androgen-dependent and castration-resistant, as indicated by the continuously increasing levels of the prostate-specific antigen (PSA)." (PMID 37511059, 2023). "In this in vitro study, we have demonstrated that in AR+ and AR− prostate cancer cells, α-lipoic acid (ALA) reduces cell proliferation by inhibiting autophagy, and efficaciously counteracts cellular migration and invasion." (PMID 38069431, 2023). "Like prostate epithelial cells, prostate cancer (PCa) cells are primarily driven by stimulation of the androgen receptor (AR)." (PMID 37810962, 2023). "Currently, there are two generations of AR antagonists that differ slightly in mechanism, but both inhibit testosterone-induced AR nuclear translocation and resultant transcription cascade, preventing prostate cancer cell growth." (PMID 37273124, 2023). "While the AR has a critical role in male development and physiology, it is a pivotal regulatory molecule in prostate cancer (PCa)." (PMID 37626712, 2023). "Although second-generation AR antagonists have improved the overall survival of patients with prostate cancer, both androgen-dependent and CRPC, but potential side effects have been reported." (PMID 37744273, 2023).